RN7SL523P (RNA, 7SL, cytoplasmic 523, pseudogene)
Gene: Miscellaneous RNA gene on chromosome 14 (100,319,073 to 100,319,370, reverse strand). Ensembl gene ENSG00000243976.
Homologues: Orthologues: chimpanzee Metazoa_SRP (98% identical), macaque Metazoa_SRP (91% identical). Paralogues in human: RN7SL2 (82% identical), RN7SL1 (81% identical), RN7SL3 (80% identical), RN7SL213P (79% identical), RN7SL239P (79% identical), RN7SL478P (78% identical), RN7SL398P (78% identical), RN7SL127P (78% identical), RN7SL333P (78% identical), RN7SL556P (78% identical), RN7SL709P (78% identical), RN7SL732P (78% identical), and 700 more.